CXCR4 (C-X-C motif chemokine receptor 4)
Diseases named in the same sentence as CXCR4 in open-access papers (continued):
Sharing a sentence is not in itself a finding about the gene and the disease.
tumor (continued). "CXCR4 overexpression has been reported in gastric adenocarcinoma, and its expression is associated with high tumour stage, poorer prognosis, larger tumour size, lymphatic invasion and carcinomatosis." (PMID 36140541, 2022). "POL5551, as a peptidic CXCR4 antagonist, enhanced the susceptibility of tumor cells to anoikis by mobilizing tumor cells into surrounding blood and significantly reduced distant metastasis in TNBC in situ model." (PMID 35414025, 2022). "The underlying mechanism of CXCR4 expression in tumor progression and metastasis has been investigated over the years." (PMID 35729596, 2022). "Doxorubicin, commonly prescribed chemotherapy agents, can increase the risk of migration and invasion of tumor cells through overexpression of the CXCR4 gene by affecting downstream signaling pathways." (PMID 35342925, 2022). "This has led to research into other therapeutic avenues including the use of novel therapies targeting small molecules (chemokines), the most studied one being CXCR4, which is implicated in tumour cell migration and the formation of metastasis in HNSCC." (PMID 36140541, 2022). "The studies focusing on the role of macrophages have shown that tumor-associated macrophages (TAMs) play a dominant role in mediating CXCL12/CXCR4-induced liver metastasis of CRC." (PMID 36230645, 2022). "This means positive CXCR4 expression on OS was associated with higher tumor stages (III and IV), and more likely to appear in femur or tibia as its primary site." (PMID 36816176, 2022). "In oncologic disease, CXCR4 has been found to be frequently overexpressed in malignant cells and linked to primary tumor growth, angiogenesis, tumor invasion of surrounding tissues, and metastasis." (PMID 36559044, 2022). "CXCL12/CXCR4 was reported to drive the accumulation of tumor-associated macrophages in the tumor environment or egress to draining lymphatics." (PMID 35615089, 2022). "Targeting the CXCL12/CXCR4 axis in multiple cancer models, including prostate and breast cancer, reduces tumor burden and metastatic susceptibility by preventing TAM infiltration." (PMID 36303138, 2022). "This correlation was expected because, according to the literature, CXCR4 is mainly expressed in highly malignant tumours and is associated with rapid tumour growth, early metastasis, and poor patient outcomes." (PMID 35799158, 2022). "Its receptor CXCR4 is overexpressed in many tumor types and the associated consequences vary widely." (PMID 34503058, 2021). "CXCR4 activation on tumor cells is associated with increased metastasis in several cancers by promoting invasion, tumor cell proliferation, matrix degradation, and neoangiogenesis." (PMID 34207884, 2021). "MMP-9 levels are substantially lower in CXCR4-deficient cells, and CXCR4 down-regulation reduces tumor development in vivo." (PMID 33946372, 2021). "Recent analysis has also shown an indispensable role of the CXCR4/let-7a/HMGA2 pathway in tumor-associated phenotypes and chemoresistance of PC cells to GEM." (PMID 34453639, 2021). "CXCR4 is highly expressed in both tumor and stromal cells in various tumor types; its overexpression is associated with poor prognosis and survival in the contexts of various cancer types." (PMID 33753481, 2021). "It is possible that the chronic and permanent loss of tumor cell-derived CXCR4 in vivo reduced the number of tumor-restraining CAFs, while increasing the proportion of tumor-promoting CAFs." (PMID 34298706, 2021). "Especially, ICAM1, THY1, and CXCR4 showed strongly positive correlations with tumor-associated macrophages." (PMID 34113647, 2021). "CXCR4 strikingly expressed in tumour cells, and CXCR4 expression was closely associated with the level of EMT‐associated proteins and Schwann cell hallmarks at nerve invasion frontier in SACC." (PMID 34170080, 2021).
tumor (continued). "CXCR4 emerged as the most prominent receptor expressed on many different cell types within the tumor and associated with various tumorigenic processes such as angiogenesis, cancer cell invasion and resistance to treatment." (PMID 35008294, 2021). "In CRC, the expression of CXCR4 in primary tumor cells is associated with recurrence, metastasis, and survival." (PMID 34298991, 2021). "The activation of CXCR4 on a tumor cell also causes an increase in VEGF-C expression, leading to lymphangiogenesis." (PMID 33467722, 2021). "From a clinical perspective, enhanced CXCR4 tumor expression is associated with poor prognosis, lower 5-year OS, and a greater chance of developing lymph node metastasis and liver recurrence in patients afflicted with PC." (PMID 34453639, 2021). "Here we show that CXCR4 activation, so far associated only with tumor progression and metastasis, also flags tumor cells to immune recognition." (PMID 33956406, 2021). "To gain insight into the possible role of the CXCL12/CXCR4/CXCR7 axis in tumor development and progression, we explored any association between the expression of the two receptors, or of their ligand, and the clinical characteristics of ACC patients." (PMID 34834449, 2021). "Perivascular CAF-derived CXCL12 is also implicated in attracting CXCR4+ macrophages toward blood vessels, which in turn leads to tumor cell intravasation in murine models." (PMID 34203869, 2021). "CXCR4 is a viable target in cancer therapy, because it mediates cancer metastasis by inducing the migration of tumor-associated cells." (PMID 34361141, 2021). "CXCR4 overexpression and dysfunctional downstream signaling have been linked to tumor development, vascularization, and metastasis in a variety of malignancies." (PMID 34943797, 2021). "These nanoplexes served as a carrier for targeting miRNA to tumor-associated cells that express CXCR4." (PMID 34361141, 2021). "It has been reported that the activation of the CXCR1/CXCR2 or CXCR4/CXCR7 pathways is associated with tumor aggressiveness and poor prognosis." (PMID 34233297, 2021). "Another approach to studying CXCL12 and its receptor CXCR4 took advantage of the fact that CXCR4 is the most commonly expressed chemokine receptor in most cancers and has been linked to tumor spread and poor prognosis." (PMID 34833360, 2021). "In gastric cancer, CXCR4+ CSCs are associated with tumor formation and ascites accumulation, serving as a tool for patient stratification." (PMID 33530455, 2021). "CXCR4 expression has been associated with the extent of tumor cell dissemination within the patient brain (based on tumor imaging features)." (PMID 35008294, 2021). "Specifically, CXCR4 participates in the regulation of cancer progression by regulating both tumor immune-microenvironment, cancer-associated fibroblasts and cancer cell functions." (PMID 34180759, 2021). "The relevance between CXCR4 level and clinicopathologic features showed that CXCR4 level was noticeably associated with tumour location, clinical staging, histological subtype, implication of resection margin, relapse and metastasis (P < .05)." (PMID 34170080, 2021). "CXCR4 is highly expressed in various tumor subtypes and is associated with tumor cell chemotaxis, invasion, and proliferation." (PMID 34503103, 2021). "This inhibition was associated with a significant suppression of the tumor CXCR4/CXCR7 and the stimulation of human CXCL12 expression." (PMID 34834449, 2021). "Chemokine receptor 4 (CXCR4), a seven-transmembrane G protein, has been implicated to mediate the metastasis of several tumors and has become a potential target for tumor therapy." (PMID 32974202, 2020).
tumor (continued). "Our studies are the first to have measured CXCR4 in matched isolated malignant colonocytes and tumor-associated stroma by Western blotting." (PMID 32110952, 2020). "Upregulation of CXCR4 expression has been observed in different human cancers, and the CXCL12/CXCR4 axis is often considered a hallmark of cancer aggressiveness and correlates with tumor size, grade and recurrence, poor prognosis and low survival." (PMID 32784743, 2020). "Subsequent studies found that tumor-derived MIF increases the expansion and migration of anti-tumor Th17 cells in nasopharyngeal carcinoma through CXCR4 which ultimately was associated with a more favorable clinical outcome." (PMID 33324425, 2020). "Administration of AMD3100 caused a 4.5-fold reduction in the tracer uptake in the tumor of irradiated animals (0.24 ± 0.1 % ID/g, p < 0.001), suggesting that tracer uptake is indeed due to CXCR4-mediated chemotaxis." (PMID 31802362, 2020). "CXCR4, a classical transmembrane G protein-coupled receptor, has been associated with more aggressive tumor phenotypes and poor prognosis in several cancer types." (PMID 33281749, 2020). "Another study also indicated that fusion between tumor cells of ovarian and lung origin and myeloid lineage cells leads to a significantly higher expression of chemokine receptor CXCR4, which is associated with the migration of tumor cells to the bone marrow." (PMID 32182935, 2020). "In particular, CXCR4 has been implicated in both tumor cell dissemination from the primary site and intravasation via trans-endothelial migration." (PMID 32483419, 2020). "As a result, treatment with the CXCR4 antagonist caused a strong reduction in the tumor uptake of N-[11C]methyl-AMD3465 in irradiated mice." (PMID 31802362, 2020). "In a Chinese population, the expression of CXCR4 in tumor cells was positively associated with tumor status and clinical stage 42." (PMID 32742450, 2020). "The SDF-1α/CXCR4 axis is associated with tumor aggressiveness, high metastatic potential, and poor prognosis." (PMID 32344892, 2020). "Cxcr4 has also been implicated in the recruitment of neutrophils and G-MDSCs to cancer cells in mouse xenograft models, resulting in tumour-promoting effects." (PMID 32325966, 2020). "The CXCR4 expression level was found to be significantly associated with tumor purity and positively correlated with the infiltration of B-cells, CD4+ T-cells, CD8+ T-cells, macrophages, neutrophils, and dendritic cells." (PMID 33194726, 2020). "As LASP1 is an adaptor protein it is likely that its loss prevents critical protein-protein interactions downstream in the CXCR4 signaling pathway, leading to the loss of the ability of tumor cells to invade through Matrigel®." (PMID 32872485, 2020). "Another study showed that primary tumors induce accumulation of B cells in the tumor-draining lymph nodes and release of pathogenic IgG that induces CXCR4 expression in cancer cells." (PMID 33096815, 2020). "High levels of CXCR4-expressing OV6+ tumor-initiating cells in HCC patient livers are associated with aggressive pathobiology, increased invasion, metastasis, and poor prognosis." (PMID 33718121, 2020). "The nuclear and cytoplasmic CXCR3 and CXCR7 correlated better with invasion, whereas the nuclear and cytoplasmic CXCR4 were both independently associated to tumour stage and survival." (PMID 32512633, 2020). "Recently, a study on circRNAs targeting CXCR4 expression has revealed the association between tumor cells and TAM infiltration." (PMID 32943996, 2020). "For example, increased expression of CXCR4 has been associated with accelerated tumor progression and tumor cell proliferation." (PMID 32368286, 2020). "Aberrant expression of CXCR4 is associated with osteoclastogenesis and tumor growth in MM through its cross-talk with various important cellular signaling pathways." (PMID 32481533, 2020).
tumor (continued). "While CXCR4 expression was lower in stromal cells, tumor-associated stromal cells expressed CXCR4 more strongly than normal stromal cells." (PMID 32110952, 2020). "Since the escape of stem cells from anti-cancer therapy is considered a major cause of treatment failure and relapse, CXCR4-directed therapy with preserved anti-tumor immunity in the tumor microenvironment would be potentially effective." (PMID 32972006, 2020). "Nuclear expression of CXCR4 has been shown to impact prognosis in several tumor models, associating both with poorer and improved outcome." (PMID 32758242, 2020). "Compelling evidence has demonstrated that CXCL12/CXCR4/CXCR7 axis is implicated in tumor growth, survival, angiogenesis, metastasis, tumor microenvironment, and chemoresistance." (PMID 33363463, 2020). "Treatment of CA-4-NPs to the tumor tissue in mice increased the CXCR4 expression due to hypoxic conditions caused by CA-4-NPs." (PMID 32486408, 2020). "The chemokine receptor CXCR4 is overexpressed by many cancer types and associated with tumor progression and the metastatic potential of the tumor." (PMID 31802362, 2020). "In xenograft tumours and clinical samples, loss of Prrx1 was negatively correlated with increased expression of CXCR4 in lung metastatic sites compared with that in the primary foci." (PMID 31752959, 2019). "Considering that the safety/tolerability assessment is based on repeat dosing once every 3 weeks, we defined MED as the lowest tested single dose causing tumour regression sustained for 3 weeks, in the SoC- and CXCR4 antibody- resistant MOLP-8 xenograft model." (PMID 30792442, 2019). "In many studies, it has been demonstrated, that elevated CXCR4 expression is associated with rapid tumor progression, high invasiveness, early metastasis, and poor patient outcome." (PMID 30867449, 2019). "Chemokine receptor-4 (CXCR4) is implicated in several pathological processes, including autoimmune disease, infection, and tumor development." (PMID 31620068, 2019). "In another example, our data suggests that tumour type susceptibility to anti-CXCR4 ADCs is also determined by tumour anatomical location and associated CXCL12 levels." (PMID 30792442, 2019). "Correspondingly, in GEP-NEN SST2A positivity of the tumor has been associated with better patient outcome, whereas presence of CXCR4 has been related to low overall survival." (PMID 30867449, 2019). "In contrast to CXCR7 knocked-down tumors, sh-CXCR4 tumors grew less than control tumors, in accordance with the significant reduction in the percentage of proliferating tumor cells observed in the CXCR4-deficient tumors." (PMID 30874597, 2019). "As a proof of concept of TAITN, the inhibition of CXCR4 caused angiogenic inhibition, whereby the surrounding tumor tissue was induced with hypoxia and became necrotic." (PMID 31336612, 2019). "In the present study, the results of Western blot and immunohistochemistry both showed that CLG significantly decreased SDF-1α and CXCR4 of the transplanted tumor, which, at least partly, underlies the protective effect of CLG on CRC metastasis." (PMID 30789971, 2019). "Total cell-associated activity better predicted in vivo tumor uptake than did the docking score or apparent CXCR4 affinity." (PMID 31022852, 2019). "The association between CXCR4 protein levels and tumor relapse (FET p = 0.031) was confirmed in luminal B BC patients of the validation cohort (FET p = 0.031)." (PMID 29849822, 2018). "Overexpression of CXCR4 has been implicated in tumour metastasis and has been found to metastasise to tissues with a high concentration of CXCL12, such as lungs, liver and bone marrow." (PMID 29959873, 2018). "Altered expression of CXCR4 has been reported in several inflammatory disorders and a variety of cancers, where it is associated with proliferation of tumor cells and disease progression." (PMID 29682201, 2018).
tumor (continued). "CXCR4 antagonist plerixafor combined with anti-PD-1 therapy showed the most pronounced tumor growth delay, and was associated with increased intratumoral penetration and activation of CD8+ T lymphocytes." (PMID 30622535, 2018). "We focused on signaling by chemokine CXCL12, a hallmark molecule secreted by CAFs, and receptor CXCR4, a driver of tumor progression and metastasis in TNBC." (PMID 29416611, 2018). "Tumor associated N2 neutrophils are characterized by high expression of CXCR4, VEGF, and gelatinase B/MMP9 and can be induced on exposure to high TGF-β levels." (PMID 30304046, 2018). "CXCR4 is also elevated in prostate, breast, and melanoma cancer cells and tissue compared normal samples, and is associated with tumor stage, a metastatic phenotype, and poor survival." (PMID 29642534, 2018). "In CCC, on the other hand, tumor diameter was positively associated with intensity of CXCR4 expression of the tumor cells (rsp = 0.762, p < 0.001)." (PMID 29282035, 2017). "Treating the cells with HT-EA reversed the COX2 or CXCR4 expression-associated increase in tumor cell invasion." (PMID 27974694, 2017). "Overexpression of this receptor has been observed in more than 20 different tumor entities and many studies demonstrated that increased CXCR4 expression is associated with rapid tumor progression, high invasiveness, early metastasis, and poor patient outcomes." (PMID 29282035, 2017). "Recently, CXCR4 came into focus in different tumor entities and CXCR4-positivity was usually associated with local tumor growth, the occurrence of local and systemic metastases and, therefore, reduced survival parameters." (PMID 29348861, 2017). "The activation of molecular pathways, such as Akt and ERK, induces tumor progression and is associated with CXCR4 expression." (PMID 28415580, 2017). "The crescent hypoxia is also associated with crescent production of CXCR4 mRNA, a potent angiogenic and tumor progression inducer." (PMID 29262564, 2017). "ccRCC patients with VHL gene mutations revealed an association between strong CXCR4 expression and poor tumor-specific survival." (PMID 28846693, 2017). "CXCR4 positive specimens demonstrated a significant increased risk for tumor recurrency associated death (rT: HR 10.07; p=0.001 / rN: HR 5.04; p=0.013 / rM: HR 2.49; p=0.029) when compared with their unaltered counterparts." (PMID 29348861, 2017). "The CXCR4 pathway has been shown to be associated with tumor progression and poor prognosis in many types of cancer including breast, lung, colon, melanoma and soft tissue sarcomas." (PMID 28191313, 2017). "CXCL12 is known to mediate normal cell migration and is implicated in many neoplasias, including the overexpression of its canonical receptor, CXCR4, in various cancers." (PMID 29250030, 2017). "Depending on the tumor type, expression of CXCR4 has been reported in 20%-80% of cases, where it has been implicated in multiple processes, including tumor growth, invasion of adjacent tissue, metastasis, and resistance to therapy." (PMID 29088715, 2017). "The chemokine CXCL12 and its receptor CXCR4 has been demonstrated to cause tumor progression and metastasis." (PMID 28658303, 2017). "The increased risk can be identified by CXCR4 over-expression at primary tumor site, providing a diagnostic approach to improve treatment stratification." (PMID 29348861, 2017). "C-X-C chemokine receptor 4 (CXCR4) is over-expressed in multiple human cancers and correlates with tumor aggressiveness, poor prognosis and increased risk for distant metastases." (PMID 28566721, 2017). "Through this methodology the author affirms that CXCR4 expression increases the risk of tumor metastases, while CXCR7 expression is associated with shorter survival." (PMID 28439237, 2017).